MTND1P23 (MT-ND1 pseudogene 23)
Gene: Unprocessed pseudogene on chromosome 1 (629,062 to 629,433, forward strand). Ensembl gene ENSG00000225972.
Diseases named in the same sentence as MTND1P23 in open-access papers:
MTND1P23 is named in the same sentence as 3 diseases in open-access papers, as found by Europe PMC text mining. Sharing a sentence is not in itself a finding about the gene and the disease. The quoted sentences say what the papers report.
epilepsy (1 paper, 2024). A brain disorder characterized by episodes of abnormally increased neuronal discharge resulting in transient episodes of sensory or motor neurological dysfunction, or psychic dysfunction. "However, studies on the role of MTND1P23 in epilepsy remain inadequate." (PMID 38572804, 2024).
schizophrenia (1 paper, 2024). A major psychotic disorder characterized by abnormalities in the perception or expression of reality. "From total 66 DEGs, we identified 11 (16%) as pseudogenes, which comprised two main groups: mitochondrial pseudogenes increased in females (MTND1P23, MTCO1P12, MTCO1P40, and MTND2P28) and ribosomal pseudogenes increased in male schizophrenia patients (RPS4XP22, RPS16P4, and RPS28P7)." (PMID 39068467, 2024).
tumour (1 paper, 2024). "In particular, genes such as MTND1P23, PLCH2, RNF223, PERM1, TAS1R3, and specific TMEM genes exhibit varied levels of expression across different tumour stages, thereby presenting a potential to discern early-stage ESCC from its later stages." (PMID 38562378, 2024).